ZFAS1 (ZNFX1 antisense RNA 1)
Synonyms: HSUP1; HSUP2; C20orf199; NCRNA00275; ZNFX1-AS1
Gene: Long non-coding RNA gene on chromosome 20 (49,277,054 to 49,299,600, forward strand). Ensembl gene ENSG00000177410.
Gene Ontology:
Biological process: RNA processing
Cellular component: cytoplasm; nucleolus; nucleus
Diseases named in the same sentence as ZFAS1 in open-access papers:
ZFAS1 is named in the same sentence as 111 diseases in open-access papers, as found by Europe PMC text mining. Sharing a sentence is not in itself a finding about the gene and the disease. The quoted sentences say what the papers report.
colorectal cancer (55 papers, 2016 to 2026). A primary or metastatic malignant neoplasm that affects the colon or rectum. "In colorectal cancer, the upregulated level of ZFAS1 is directly associated with poor prognosis and promotes invasion and metastasis." (PMID 36770654, 2023). "In angiogenesis regulation, colorectal cancer studies demonstrate ZFAS1-mediated VEGFA activation via miR-150–5p sequestration, promoting AKT/mTOR-dependent vascularization." (PMID 41450817, 2026). "ZFAS1 has been widely proved to be related with the development and progression of human cancers, including colorectal cancer, nasopharyngeal carcinoma, oral squamous cell carcinoma, pancreatic cancer, and so on." (PMID 38218807, 2024). "For example, ZFAS1 facilitates colorectal cancer cell proliferation, migration, and increased cell apoptosis." (PMID 39296014, 2024). "ZFAS1 facilitates the advancement and metastasis of colorectal cancer by serving as a competing endogenous RNA of miR-144 to modulate EZH2 expression." (PMID 39296014, 2024). "In cancers, ZFAS1 is thought to be overexpressed in most human cancers, including nonsmall cell lung cancer, colorectal cancer, glioma, hepatocellular carcinoma and head and neck cancer." (PMID 36855431, 2023). "The ZFAS1 is involved in colorectal cancer progression by inducing vascular endothelial growth factor A (VEGFA), which is one of the important inducers of angiogenesis in tumors." (PMID 36770654, 2023). "Zinc Finger NFX1-Type Containing 1 (ZFAS1) can forecast the clinical outcome of patients with different neoplasms including colorectal cancer, gastric cancer, and other types of cancer." (PMID 37302999, 2023). "Upregulation of ZFAS1 induces colorectal cancer cell migration, invasion, and metastasis and is positively correlated with TNM stage these tumors." (PMID 36770654, 2023). "ZFAS1 was shown to regulate colorectal cancer progression by interacting with the miR-150-5p/VEGFA axis." (PMID 35112985, 2022). "For example, the ZFAS1 was reported to promote the tumorigenesis and development of colorectal cancer by regulating the DDX21-POLR1B axis, while its aberrant expression is associated with prognosis and chemosensitivity in cervical cancer." (PMID 35090549, 2022). "For example, long ncRNA ZFAS1 promotes snoRNA-mediated 2′-O-methylation through Nop58 recruitment and is involved in the development and prognosis of colorectal cancer." (PMID 35790714, 2022). "The N6-methyladenosine reader IMP2 stabilizes the ZFAS1/OLA1 axis and activates the Warburg effect, which is implicated in colorectal cancer." (PMID 36175504, 2022). "m6A modification promotes mitochondrial energy metabolism in the pathogenesis of colorectal cancer by both stabilizing the ZFAS1/OLA1 axis and activating the Warburg effect." (PMID 36175504, 2022). "Although the ZFAS1 knockdown decreases cell proliferation and invasion of colorectal cancer in vitro and in vivo, the direct implication of SNORDs and rRNA 2′Ome has not been demonstrated." (PMID 34440717, 2021). "In a panel of human colorectal cancer cell lines, it appeared that the depletion of ZFAS1 decreases the level of rRNA 2′Ome at 28S-Gm3878 and 28S-Gm4593, guided by SNORD12C and SNORD78, respectively." (PMID 34440717, 2021). "ZFAS1 has been shown to promote colorectal cancer progression through competitively binding to miR-150-5p and upregulation of VEGFA." (PMID 34703899, 2021). "Meanwhile, it has been reported that lncRNA ZFAS1 contributes to the metastasis of colorectal cancer by regulating miR-34b/SOX4 axis." (PMID 34496348, 2021). "Previous experiments describe the clinical relevance and the mechanisms of action of ZFAS1 in colorectal cancer cell lines, but it is important to explore its mechanism of action in vivo." (PMID 33771981, 2021).
colorectal cancer (continued). "Recent studies have shown that ZFAS1 was overexpressed and promoted the malignant progress of many tumour types such as colorectal cancer, oesophageal squamous cell carcinoma and osteosarcoma." (PMID 34552050, 2021). "For example, lncRNA ZFAS1 has been identified as a regulator of colorectal cancer cell migration and invasion and its overexpression connects to shorter overall survival of colorectal cancer patients." (PMID 33483471, 2021). "Knockdown of ZFAS1 can block the cell cycle of colorectal cancer cells in the G1 phase, thereby inhibiting the proliferation of colon cancer cells." (PMID 32025520, 2020). "Overexpression of ZFAS1 promoted cell proliferation, invasion, and induced cell apoptosis in colorectal cancer (CRC)." (PMID 30288832, 2019). "ZFAS1 was dysregulated in breast cancer, gastric cancer, and colorectal cancer, and played as an oncogene in cancer progression though promoting cancer metastasis, growth and EMT." (PMID 30873207, 2019). "ZFAS1 has been found in several studies to be overexpressed in colorectal cancer tissues and cell lines compared with paired adjacent normal colorectal tissues and a human colonic epithelial cell line, HCoEpiC." (PMID 30288832, 2019). "Upregulation of ZFAS1 expression was positively associated with advanced TNM stage and lymph‐node metastasis in colorectal cancer, gastric cancer, ovarian cancer, and NSCLC." (PMID 30288832, 2019). "Overexpression of ZFAS1 was shown to promote cell proliferation and induced cellular apoptosis in various cancers, including colorectal cancer, gastric cancer, glioma, osteosarcoma, acute myeloid leukaemia, and ovarian cancer." (PMID 30288832, 2019). "Recent studies reveal that ZFAS1 is highly expressed in hepatocellular carcinoma and colorectal cancer, promotes metastasis and tumorgenicity by involving in cell cycle." (PMID 31096997, 2019). "Consistent with our findings in T-ALL, ZFAS1 was highly expressed in liver cancer, colorectal cancer and was critical for cell metastasis by regulating miR-150 to abrogate its tumor-suppressive function." (PMID 31096997, 2019). "Positive regulation of EMT, manifested as down-regulation of epithelial markers (e.g. E-cadherin) and up-regulation of mesenchymal markers (e.g. vimentin), by knockdown of ZFAS1 has been demonstrated in glioma, colorectal cancer and gastric cancer." (PMID 30186041, 2018). "ZFAS1 has been found to be upregulated and function as oncogene in colorectal cancer and hepatocellular carcinoma, but its expression pattern, biological function and underlying mechanism in gastric cancer is still undetermined." (PMID 27246976, 2017). "For instance, ZFAS1 is significantly up-regulated in colorectal cancer tissue, and ZFAS1 silencing decreases tumor proliferation with G1-arrest via interacting with cyclin-dependent kinase 1 (CDK1)." (PMID 29262629, 2017). "For example, altered expression of ZFAS1 has been reported in breast, liver, gastric, lung, glioma, ovarian and colorectal cancers." (PMID 28938617, 2017). "Most recently, dysregulation of ZFAS1 have been observed in patients with acute myocardial infarction and various human cancers, including breast cancer, colorectal cancer, gastric cancer and hepatocellular carcinoma." (PMID 28099946, 2017). "In vitro, ZFAS1 suppression decreased cell migration and invasive ability of colorectal cancer cells." (PMID 29163829, 2017). "Previously, ZFAS1 was reported to be upregulated in colorectal cancer and hepatocellular carcinoma, but to be upregulated in breast cancer." (PMID 28099946, 2017). "The expression of ZFAS1 in colorectal cancer was high and significantly related to lymphatic metastasis." (PMID 28938617, 2017).
colorectal cancer (continued). "In contrast, ZFAS1 was also reported to be significantly upregulated in colorectal cancer compared to paired normal tissues." (PMID 28099946, 2017). "We determined expression of 83 long non-coding RNAs (lncRNAs) and identified ZFAS1 to be significantly up-regulated in colorectal cancer (CRC) tissue." (PMID 26506418, 2016). "Using Lncbase, we predicted that ZFAS1 targets miR-588 in DN which abnormal expression has been reported to be involved in the pathogenesis of prostate cancer, human breast cancer, colorectal cancer, hepatocellular carcinoma, and osteosarcoma, but not in DN." (PMID 35090549, 2022). "Over 3000 studies have reported that lncRNAs function as sponges to interact with miRNAs; for example, lncRNA ZFAS1 can sponge miR-150-5p to upregulate VEGFA expression to contribute to the progression of colorectal cancer, yet other regulatory mechanisms of lncRNAs are few reported." (PMID 34980188, 2022). "Similarly, it has been reported that ZFAS1 participates in the progression of colorectal cancer through the miR-150-5p/VEGFA axis." (PMID 34552050, 2021). "ZFAS1 is related to multiple types of tumors, such as breast cancer, renal cell carcinoma, gastric cancer, and colorectal cancer." (PMID 35198599, 2021). "ZFAS1 has been reported to be involved in several cancers, including hepatocellular carcinoma, osteosarcoma, breast cancer, and colorectal cancer, by modulating cell proliferation and migration." (PMID 34268302, 2021). "The expression of lncRNA ZFAS1 is increased in colorectal cancer tissues." (PMID 32025520, 2020). "Accumulating evidence has demonstrated the abnormal expression of ZFAS1 in multiple cancers, including gastric cancer, hepatocellular carcinoma, colorectal cancer, glioma, osteosarcoma, ovarian cancer, acute myeloid leukaemia, NSCLC, oesophageal squamous cell carcinoma, and breast cancer." (PMID 30288832, 2019). "Additionally, increased expression of ZFAS1 was closely correlated with poorer overall survival in colorectal cancer, gastric cancer, glioma, osteosarcoma, oesophageal squamous cell carcinoma, ovarian cancer, and NSCLC." (PMID 30288832, 2019). "Such as, ZFAS1 sponges miR-484 to promote cell proliferation and invasion in colorectal cancer." (PMID 31781561, 2019). "Various studies have identified ZFAS1 as a cancer oncogene in: glioma, gastric cancer, colorectal cancer, hepatocellular carcinoma, ovarian cancer, melanoma, non-small cell lung cancer, osteosarcoma, esophageal squamous cell carcinoma, and hematological malignancies." (PMID 31010087, 2019). "Interestingly, knockdown of ZFAS1 inhibited cell migration and invasion in colorectal cancer, gastric cancer, glioma, hepatocellular carcinoma, osteosarcoma." (PMID 30288832, 2019). "In colorectal cancer, lncRNA ZFAS1 may function as an oncogene by modulating ZEB1 to induce the expression of EMT, or combing with CDK1 and sponging with miR-590-3p to inhibit apoptosis." (PMID 28977885, 2017). "Similarly, elevated ZFAS1 expression was observed in colorectal cancer patients, and correlated with lymphatic invasion, advanced TNM stages, and poor survival." (PMID 29163829, 2017). "Recent research has also found that ZFAS1 acts as an oncogene in colorectal cancer." (PMID 28938617, 2017).
colorectal cancer (continued). "Examples include promotion of oesophageal adenocarcinoma cells invasion and metastasis by HNF1A-AS1, control of colorectal cancer cells apoptosis by ZFAS1, reprogramming of induced pluripotent stem cells by RNA-RoR, and regulation of non-small cell lung cancer cells growth and apoptosis by MEG3." (PMID 26848625, 2016). "For example, the host gene lncRNA ZFAS1, which encodes three C/D box SNORD12 family members (SNORD12, SNORD12B, SNORD12C), was observed to be significantly overexpressed in a variety of human malignancies such as colorectal cancer, hepatic cancer, and gastric cancer, etc.." (PMID 32443980, 2020). "Also, the lncRNA ZFAS1 promotes colorectal cancer cell proliferation via sponging this miRNA48." (PMID 31182759, 2019). "In recent years, ZFAS1 high expression has been proven as an unfavorable prognostic biomarker for many types of cancers including lung cancer, hepatocellular carcinoma, osteosarcoma, glioma, colorectal cancer, gastric cancer, esophageal squamous cell carcinoma, and ovarian cancer." (PMID 29678899, 2018). "Therefore, ZFAS1 is an independent prognostic factor of recurrence and death for colorectal cancer patients, and down-regulation of ZFAS1 could inhibit migration and invasion of intestinal cancer cells." (PMID 28938617, 2017). "However, recent studies have shown that ZFAS1 is upregulated in multiple types of tumors, including hepatocellular carcinoma, gastric cancer, and colorectal cancer, suggesting that ZFAS1 may serve as a proto-oncogene, and a prognostic biomarker in cancer." (PMID 29163829, 2017). "The ZFAS1 lncRNA and snoRNP NOP58 are upregulated in colorectal cancer (CRC), and ZFAS1 interacts with NOP58, which results in the binding of SNORD72C and SNORD78 to mediate 2′-O-Me at the Gm3878 and Gm4593 sites in rRNA." (PMID 38871819, 2024). "The alteration on these modifications impacts on the stability and translation of downstream targets of ZFAS1 (such as EIF4A3 and LAMC2), which directly impacts the development of colorectal carcinoma (CRC)." (PMID 38406265, 2024). "Moreover, SP1 could combine with the promoter of ZFAS1 to regulate ZFAS1 in colorectal cancer." (PMID 34268302, 2021). "It has been proposed that ZFAS1 is a key activator of the EMT process in glioma, colorectal cancer, and gastric cancer." (PMID 31010087, 2019). "However, ZFAS1 has been suggested to be overexpressed in most types of human cancers such as lung cancer, hepatocellular carcinoma, osteosarcoma, glioma, colorectal cancer, gastric cancer, esophageal squamous cell carcinoma, ovarian cancer, prostate cancer, and acute myeloid leukemia." (PMID 29678899, 2018). "Contrastingly, accumulating evidence identifies ZFAS1 as a context-dependent oncogene, showing marked overexpression in HCC, gastric cancer, and colorectal cancer where it drives tumor progression via regulation of proliferation, angiogenesis, and metastatic dissemination." (PMID 41450817, 2026). "Knockdown of ZFAS1 decreases the RNA stabilization of SNORD12C/78 and NOP58 through binding with snoRNP to induce 2′-O-Me of 28S rRNA, which eventually inhibits the proliferation and invasion of colorectal cancer cells." (PMID 36829433, 2023). "Specifically, ZFAS1 knockdown results in decreased RNA stabilization of NOP58, SNORD12C/78, and their 2′-O-Me modification guidance, and this subsequently inhibits colorectal cancer (CRC) cell proliferation and invasion and promotes cell apoptosis in vitro and in vivo." (PMID 32443980, 2020). "Furthermore, ZFAS1 increased VEGFA expression by binding to miR-150-5p via activating EMT and Akt/mTOR signaling pathways to promote the development of colorectal cancer." (PMID 33202381, 2020). "Meanwhile, in colorectal cancer and HCC, ZFAS1 regulated tumor metastasis." (PMID 31781169, 2019).
colorectal cancer (continued). "Studies in hepatocellular carcinoma and colorectal cancer have found that ZFAS1 is more highly expressed in these cancers as compared to normal tissues, and that higher expression of ZFAS1 is associated with tumour metastasis and poor patient prognosis." (PMID 27871336, 2016). "RNA immunoprecipitation (RIP) assays indicated that ZFAS1 enhanced PABP2 binding with SREBP1 mRNA, which stabilizes SREBP1 mRNA and augments transcription of SCD1 and FASN, finally leading to accelerated lipid accumulation and promotion of the malignant phenotype of colorectal cancer cells." (PMID 35036050, 2022). "Despite the emerging knowledge regarding the roles of lncRNA ZFAS1 in cancers, the expression landscape, regulation network, and function manner with target proteins such as DDX21/POLR1 family have not been investigated in regard to colorectal cancer." (PMID 33202381, 2020).